RNU6-860P (RNA, U6 small nuclear 860, pseudogene)
Gene: Small nuclear RNA gene on chromosome 3 (198,196,746 to 198,196,849, forward strand). Ensembl gene ENSG00000222792.
Homologues: Orthologues: macaque U6 (91% identical), pig U6 (84% identical), pig U6 (78% identical), dog U6 (77% identical). Paralogues in human: RNU6-1076P (100% identical), RNU6-1100P (100% identical), RNU6-1118P (100% identical), RNU6-1217P (100% identical), RNU6-355P (100% identical), RNU6-447P (100% identical), RNU6-785P (100% identical), RNU6-791P (100% identical), U6 (100% identical), RNU6-1054P (99% identical), RNU6-1199P (99% identical), RNU6-1319P (99% identical), and 1289 more.